NPC1L1 (NPC1 like intracellular cholesterol transporter 1)
Diseases named in the same sentence as NPC1L1 in open-access papers (continued):
Sharing a sentence is not in itself a finding about the gene and the disease.
liver fibrosis (1 paper, 2024). "Furthermore, in diabetic and obese mice, the administration of atorvastatin and ezetimibe, one reducing cholesterol production and the other its uptake by HMGCR inhibition and the Niemann–Pick C1-like 1 (NPC1L1) proteins, significantly reversed liver fibrosis of MASH mice." (PMID 39594528, 2024).
lung carcinoma (1 paper, 2023). "In this drug-target MR analysis, we assessed the effects of LLDs on lung cancer risk via six LLD targets (APOB, APOC3, HMGCR, LPL, NPC1L1, and PCSK9), comprising 12 lipid-lowering pathways." (PMID 38034491, 2023).
malaria (1 paper, 2020). Malaria is a serious and sometimes fatal disease caused by a parasite that commonly infects a certain type of mosquito which feeds on humans. "NPC1L1 is widely accepted as playing a role in the intercellular transport of cholesterol in human cells and it is possible that malaria parasites take up cholesterol into their bodies via this protein." (PMID 32066816, 2020).
male infertility (1 paper, 2024). The inability of the male to effect fertilization of an ovum after a specified period of unprotected intercourse. "In addition, the results also found that PCSK9 inhibitors increased the risk of PH, and NPC1L1, HMGCR inhibitors decreased the risk of PCa, but at the same time HMGCR inhibitors increased the risk of male infertility." (PMID 38390206, 2024).
melanoma (1 paper, 2024). A malignant, usually aggressive tumor composed of atypical, neoplastic melanocytes. "Employing Mendelian randomization, we investigated the impact of three prevalent LDL-C reduction drug targets (HMGCR, PCSK9, and NPC1L1 genes) on melanoma risk." (PMID 38974243, 2024). "IVW did not demonstrate that NPC1L1 expression show a significant association with melanoma risk [OR: 0.998 (0.001–19.998); p = 0.899]." (PMID 38974243, 2024).
Menorrhagia (1 paper, 2023). Prolonged and excessive menses at regular intervals in excess of 80 mL or lasting longer than 7 days. "Our findings also suggest that HMGCR inhibitors, but not PCSK9 or NPC1L1 inhibitors, have a protective effect on patients with menorrhagia." (PMID 38027179, 2023).
migraines (1 paper, 2023). "In contrast, ABCG5/ABCG8 enhancement, APOB inhibition, NPC1L1 inhibition, PCSK9 inhibition was found to be suggestively associated with higher risk of migraine." (PMID 37596566, 2023). "Our findings suggested the possibility, without confirmation, that exposure to bile acid sequestrants targeting ABCG5/ABCG8, cholesterol absorption inhibitors targeting NPC1L1, and Mipomersen targeting APOB might increase the likelihood of migraines in individuals." (PMID 37596566, 2023).
Nephropathy (1 paper, 2025). A nonspecific term referring to disease or damage of the kidneys. "This study evaluated the associations between genetic proxies of cholesterol-lowering drug targets (HMGCR, PCSK9, and NPC1L1) and the risk of diabetic complications, including nephropathy, retinopathy, and neuropathy." (PMID 40225015, 2025). "In this study, we employed MR to explore the causal relationships between cholesterol-lowering drug targets (HMGCR, PCSK9, and NPC1L1) and the risk of developing diabetic microvascular complications (including nephropathy, retinopathy, and neuropathy)." (PMID 40225015, 2025).
neuroblastoma (1 paper, 2025). Neuroblastoma (NB) is the most common solid, extracranial childhood tumor. "Additionally, we observed that neuroblastoma cells exhibited synergistic sensitivity to FLIX5 when combined with ezetimibe, which targets NPC1L1 and blocks intestinal cholesterol absorption." (PMID 40701975, 2025).
oropharyngeal cancer (1 paper, 2021). Carcinoma, predominantly squamous cell, arising from the epithelial cells of the oropharynx. "There was little evidence that genetically-proxied inhibition of HMGCR (target of statins), NPC1L1 (target of ezetimibe) and CETP (target of CETP inhibitors) influences oral or oropharyngeal cancer risk." (PMID 33886544, 2021).
osteonecrosis (1 paper, 2025). A none disease characterized by death of bone tissue due to a lack of blood supply.
osteoporosis (1 paper, 2025). A condition of reduced bone mass, with decreased cortical thickness and a decrease in the number and size of the trabeculae of cancellous bone (but normal chemical composition), resulting in increased fracture incidence. "In OVX mice, NPC1L1 knockdown significantly reversed osteoporosis‐related bone loss, as evidenced by improved trabecular parameters (BV/TV%, Tb.Th, Tb.N)." (PMID 40496351, 2025). "Pharmacological interventions targeting this axis, such as the use of NPC1L1 inhibitors or Cyp27a1 antagonists, may provide novel strategies to prevent or treat bone loss associated with osteoporosis." (PMID 40496351, 2025). "We also explored the role of NPC1L1 in osteoporosis (OP), focusing on the downstream C/EBPα/Cyp27a1/27‐hydroxycholesterol (27‐OHC) axis." (PMID 40496351, 2025). "Taken together, these findings indicate that NPC1L1 is an important inhibitory factor in osteogenic differentiation during osteoporosis." (PMID 40496351, 2025). "Our findings establish the NPC1L1/C/EBPα/Cyp27a1/27‐OHC axis as a key mechanism underlying cholesterol‐mediated inhibition of osteogenesis and osteoporosis development." (PMID 40496351, 2025). "To determine the role of NPC1L1 in osteogenesis and osteoporosis progression, we used a lentiviral system to introduce shRNA‐expressing plasmids into the osteoblast C3H10 and MC3T3‐E1 cell lines." (PMID 40496351, 2025). "Similarly, the gene expression profiles of femurs from postmenopausal osteoporosis patients revealed significantly increased NPC1L1 expression (GSE230665)." (PMID 40496351, 2025). "Thus, our study reveals the previously unknown role of NPC1L1 in osteogenic differentiation and osteoporosis progression." (PMID 40496351, 2025).
pancreatic adenocarcinoma (1 paper, 2026). "Their results indicated that the ectopic expression of NPC1L1 in Pancreatic Adenocarcinoma (PAAD) cells inhibited the activation and proliferation of anti-tumor CD8+ T cells within the tumor microenvironment." (PMID 41601682, 2026).
Portal vein thrombosis (1 paper, 2025). Thrombosis of the portal vein and/or its tributaries, which include the splenic vein and the superior and inferior mesenteric veins. "NPC1L1 inhibitors may also prevent the occurrence of portal vein thrombosis (PVT), a severe complication of PH." (PMID 40596422, 2025).
psoriasis (1 paper, 2023). An autoimmune condition characterized by red, well-delineated plaques with silvery scales that are usually on the extensor surfaces and scalp. "Inhibition of PCSK9 was associated with a lower risk of psoriasis, whereas inhibition of HMGCR and NPC1L1 did not have an impact." (PMID 37964871, 2023).
rectal cancer (1 paper, 2025). A primary or metastatic malignant neoplasm that affects the rectum. "NPC1L1‐mediated LDL was positively associated with rectal cancer (OR = 4.47, 95% CI: 2.31–8.65, p < 0.01)." (PMID 40443776, 2025). "Additionally, PCSK9‐mediated LDL was negatively associated with rectal cancer (OR = 0.60, 95% CI: 0.48–0.75, p < 0.01), while NPC1L1‐mediated LDL was positively associated with rectal cancer (OR = 4.57, 95% CI: 2.10–9.95, p < 0.01)." (PMID 40443776, 2025).
renal carcinoma (1 paper, 2024). A carcinoma arising from the epithelium of the renal parenchyma or the renal pelvis. "Although we assessed gene effect scores across several renal cancer cell lines, which indicated that NPC1L1 knockout significantly reduced cell survival, further validation using direct in vitro and in vivo studies is still needed." (PMID 39598242, 2024).
Ventricular arrhythmia (1 paper, 2021). "Genetic inactivation of NPC1L1 or inhibition with ezetimibe reduced blood phytosterols, inflammation, cardiac fibrosis, ventricular arrhythmias and sudden cardiac death." (PMID 34465831, 2021). "Our data indicate that blocking phytosterol absorption through NPC1L1 inhibition can reduce inflammation, cardiac fibrosis, ventricular arrhythmia and death in mice." (PMID 34465831, 2021).
viral infections (1 paper, 2022). "In addition, there are many studies reporting the importance of these cellular proteins in a number of viral infections such as hepatitis C virus (HCV) that requires a paralog of NPC1 protein named Niemann Pick C1 like 1 (NPC1L1)." (PMID 35081156, 2022).
cancer (20 papers, 2014 to 2025). A tumor composed of atypical neoplastic, often pleomorphic cells that invade other tissues. "Niemann–Pick C1-Like 1 (NPC1L1) plays a crucial role in cholesterol absorption and has been implicated in cancer progression across various cancers." (PMID 39598242, 2024). "This study identified a key role for NPC1L1 in multidrug‐resistant (MDR) cancer cells with the DTP state, where NPC1L1 orchestrated a redox signaling against the harsh environment caused by cancer therapy." (PMID 35023619, 2022). "Overall, the current studies on the connection between NPC1L1 and cancers are deficient, however, due to the function of NPC1L1 in cholesterol uptake and the link between cholesterol and cancer." (PMID 36034854, 2022). "The current research on the association between NPC1L1 and cancer in carcinogenesis and cancer therapy is of utmost importance since NPC1L1 is a crucial member of cholesterol in intestinal absorption." (PMID 36034854, 2022). "The NPC1L1 inhibitor, ezetimibe, began to be used in clinic to lower cholesterol and has caused the great debate on its role in cancer." (PMID 25881076, 2015). "Also upregulated in persistent OE19 cells was Niemann-Pick C1-like 1 (NPC1L1), which has previously been implicated in the adaptation of multidrug resistant cancer cells entering a drug-tolerant persistent state by promoting uptake of vitamin E." (PMID 40473905, 2025). "Importantly, the upregulation of NPC1L1 is positively associated with tumor progression in various cancers." (PMID 37754524, 2023). "Negative scores observed in cell lines, such as OSRC2, RCC10RGB, and CAKI2, suggest that NPC1L1 is essential for the survival of these cancer cells." (PMID 39598242, 2024). "Previous studies noticed considerably greater levels of NPC1L1 expression in cancer cells compared to normal cells." (PMID 37754524, 2023). "Cholesterol absorption in the IECs is mainly mediated by NPC1L1, and TCGA, a database of molecular signatures collected from human cancer tissues, showed that NPC1L1 was more highly expressed in human CRC rather than in normal tissues (p < 0.0001)." (PMID 36641489, 2023). "Then, using the studies that were accessible, we summarized the connection between NPC1L1 and cancer for the first time." (PMID 36034854, 2022). "In the DTP state, we confirmed the epigenetic regulation of NPC1L1 by DNA demethylation in MDR cancer cells, similar to intestinal cells, which mainly contributed to vitamin E uptake against oxidative stress." (PMID 35023619, 2022). "The significance of NPC1L1 in carcinogenesis and cancer therapy, however, merits additional research to offer new therapeutic avenues for clinical cancers due to the role of cholesterol in tumorigenesis and development." (PMID 36034854, 2022). "We therefore evaluated the efficacy of this strategy using a colony formation assay and found that siRNA‐mediated silencing of NPC1L1 resulted in a further decrease in colony formation in chemotherapy agents/verapamil‐treated MDR cancer cells." (PMID 35023619, 2022). "Further disruption of EPLIN function, or its interactions with proteins such as actin, tubulin, or NPC1L1, may lead to increased toxicity in cancer cells relative to normal cells." (PMID 40701975, 2025). "Recent studies have suggested that NPC1L1 may play a role in cancer progression, with variable expression levels reported in different cancer types." (PMID 39598242, 2024). "The majority of cell lines, including OSRC2, RCC10RGB, and CAKI2, exhibited negative gene effect scores, with the lowest score being approximately −0.4898, indicating that NPC1L1 may be essential for the survival of these cancer cells." (PMID 39598242, 2024). "Finally, statistical significance analysis of NPC1L1 expression in the normal and cancer tissues (P value for COAD: 7.1x10− 8, P value for COADREDA: 1.8x10–8) was performed using unpaired Wilcoxon rank sum and signed rank tests by R package (version 3.6.4)." (PMID 36641489, 2023).
cancer (continued). "We hypothesized that NPC1L1 inhibition in combination with chemotherapy agents/verapamil might usefully improve outcomes of current drug‐resistant reverse therapy in MDR cancer cells by directly targeting MDR persister cells." (PMID 35023619, 2022). "Therefore, ezetimibe, a drug that reduces cholesterol by inhibiting NPC1L1, is considered to be an effective and feasible therapeutic approach for cancer." (PMID 35924044, 2022). "Specific therapy targeting of MDR persister cells in the clinic may be applied by two alternative strategies: inhibition of NPC1L1 function by using ezetimibe or complete deprivation of vitamin E in cancer cells." (PMID 35023619, 2022). "NPC1L1 also has the potential to develop into a new therapeutic target and a cancer marker." (PMID 36034854, 2022). "Thus, the authors also noted that DNA methyltransferase-induced NPC1L1 silence was reduced in MDR persister cancer cells." (PMID 35301283, 2022). "The primary objective of this study was to investigate the difference in the 5-year survival between the NPC1L1 high and NPC1L1 low groups because this parameter is widely used to reflect the prognosis—and the endeavors required for the clinical management—of cancer." (PMID 34511128, 2021). "NPC1L1−/− mice had a significant lower ratio of malignant tumor/tumor than WT (p < 0.05)." (PMID 25881076, 2015). "Given the role of cholesterol in cancer and the function of NPC1L1 in cholesterol uptake, future studies focusing on this connection may provide additional targets to inhibit cholesterol-dependent cancer progression." (PMID 24533143, 2014). "Indeed, the notion that inhibiting NPC1L1 could eliminate MDR cancer cells is intriguingly interlinked with previous studies." (PMID 35301283, 2022). "Approved NPC1L1 inhibitors, such as Ezetimibe, and HMGCR inhibitors like statins, can be used in combination with anticancer drugs for cancer treatment." (PMID 40145543, 2025). "Despite its known function in lipid metabolism, the expression patterns and prognostic significance of NPC1L1 in RCC and other cancers remain largely unexplored." (PMID 39598242, 2024). "Their study illuminates the role of redox signaling in regulating the survival of DTP cancers and confirms the potential of targeting NPC1L1 by ezetimibe for treating MDR disease, thereby delaying cancer recurrence." (PMID 35301283, 2022). "Thus, the involvement of NPC1L1 in cancer development may be cancer-type specific." (PMID 34511128, 2021). "We also observed increased expression of NPC1L1 following TAX/(HA/VER@ZIF‐8) treatment by immunohistochemical staining consistent with the in vitro results, suggesting the occurrence of a DTP state in MDR cancer cells." (PMID 35023619, 2022). "This revealed NPC1L1, the direct target of the clinical hypolipidemic drug ezetimibe, as a key oxidative stress effector expressed highly in MDR persister cancer cells, contributing to enhanced uptake of vitamin E to partially counteract the combinatorial therapy‐induced oxidative stress." (PMID 35023619, 2022). "If there is a high correlation between the mRNA and protein levels among cancer cells, the protein expression of NPC1L1 in CRC may also be high in proportion to the expressed NPC1L1 transcript." (PMID 34511128, 2021). "Thus, the reduced expression of NPC1L1 may reflect its limited role in the development of RCC, potentially allowing the activation of alternative metabolic pathways critical for cancer development." (PMID 39598242, 2024). "There is, however, no comprehensive review that summarizes NPC1L1’s function in cancer." (PMID 36034854, 2022). "The role of NPC1L1 in cancer has not received much attention." (PMID 24533143, 2014).
cancer (continued). "Additionally, their findings showed that ezetimibe treatment had no impact on gemcitabine’s cytotoxicity, indicating that patients could get treated with NPC1L1 transporter protein inhibitors in addition to traditional anti-cancer medications without jeopardizing the efficacy of either." (PMID 36034854, 2022).